DPP4 (dipeptidyl peptidase 4)
Diseases named in the same sentence as DPP4 in open-access papers (continued):
Sharing a sentence is not in itself a finding about the gene and the disease.
cardiovascular disease (continued). "DPP4 inhibition is already being tested in several clinical trials in cardiovascular disease (CVD), and meta-analyses of the risks involved have proven to be varied in outcome." (PMID 29253907, 2017). "There has been increasing clinical and pre-clinical evidence showing DPP4-incretin axis is involved in cardiovascular disease." (PMID 28619058, 2017). "Some studies have already demonstrated that DPP-4 inhibitor treatment yields beneficial effects on abnormalities related to cardiovascular disease." (PMID 27809848, 2016). "DPP-4 inhibitor has been demonstrated to play a protective role in cardiovascular diseases, including hypertension, cardiomyopathy, atherosclerosis, and peripheral vascular disease via both GLP-1 dependent and independent effects." (PMID 25876091, 2015). "Although the cardiovascular effect of DPP4 inhibition has been substantially studied, the exact role of DPP4 in cardiovascular disease especially in humans remains elusive." (PMID 26075284, 2015). "Dipeptidyl peptidase-4 (DPP-4) inhibitors have been shown to have a protective effect on cardiovascular disease." (PMID 25876091, 2015). "A recent analysis stratified by renal function was performed in the SAVOR-TIMI 53 Trial, a large-scale clinical study of 16492 patients with T2DM that evaluated the impact of saxagliptin (another DPP-4 inhibitor) on cardiovascular disorders." (PMID 26137940, 2015). "Similar result was found in clinical study, enhanced serum DPP4 activity has been observed in patients with cardiovascular disease." (PMID 24416433, 2014). "However, inhibition of DPP4 also exacerbates cardiovascular disease by enhancing sympathetic activation and angiogenesis." (PMID 36831031, 2023). "Our results may support previous findings from a clinical meta-analysis, demonstrating that GLP-1 agonists were superior to DPP-4 inhibitors in suppressing cardiovascular disease mortality." (PMID 36830597, 2023). "We hypothesize that proteins downstream of DPP4 represent potential biomarkers of cardiovascular disease that inform on the senescent cell burden and constitute viable therapeutic targets." (PMID 37097759, 2023). "The SNP number rs79700168 was picked up in a microarray scanning the DPP4 gene in severely obese Caucasian individuals and was found not to be associated with cardiovascular disease in this cohort of individuals." (PMID 35413090, 2022). "DPP-4 inhibitors have shown many beneficial effects in cardiovascular diseases." (PMID 34288819, 2021). "Reduction of FABP4 level as a possible class and pleiotropic effect of DPP-4 inhibitors might be beneficial for patients with metabolic and cardiovascular diseases." (PMID 32539832, 2020). "This may explain why in this patient group DPP4 activity has a differential associative relationship with organ dysfunction compared to patients with T2DM and cardiovascular disease." (PMID 30087386, 2018). "Recently, the dipeptidyl peptidase‐4 (DPP‐4) inhibitor sitagliptin, a major anti‐hyperglycaemic agent, has received substantial attention as a therapeutic target for cardiovascular diseases via enhancing the number of circulating endothelial progenitor cells (EPCs)." (PMID 28799229, 2018). "Interestingly, DPP4 inhibition was shown to have multiple off-target effects that are potentially beneficial in the treatment of cardiovascular disease." (PMID 29253907, 2017). "DPP4 may play distinct roles in different aspects of cardiovascular disease that collectively lead to an overall neutral effect on cardiovascular events in STEMI patients." (PMID 28587613, 2017). "Since AA have been seen as a part of the spectrum of cardiovascular disease, we assumed DPP-4 inhibitor might also possess protective effects on AA." (PMID 27585542, 2016). "Recently, a novel receptor for soluble DPP4 has been identified, and data are accumulating that the adipokine-related effects of DPP4 may play an important role in the pathogenesis of cardiovascular disease." (PMID 26284071, 2015).
cardiovascular disease (continued). "But none of the polymorphisms or cardiovascular disease risk factors showed a significant correlation with DPP4 mRNA levels in omental adipose tissue." (PMID 26284071, 2015). "The vascular system, including endothelial cells, macrophages, cardiomyocytes, smooth muscle cells, valve interstitial cells, and other cell types, expresses DPP-4 widely, suggesting that it may be involved in the development and progression of cardiovascular diseases." (PMID 40429343, 2025). "However, analysis of these two different types of databases revealed that the risk of major cardiovascular disease with DPP-4 inhibitors, while undeniable, does not differ from the risk associated with metformin." (PMID 36078917, 2022). "There is a belief that DPP4 may help prevent cardiovascular disease through multiple mechanisms." (PMID 34489872, 2021). "Both DPP-4 inhibitors and GLP-1 RAs have demonstrated safety in robust cardiovascular outcome trials, while several GLP-1 RAs have been shown to significantly reduce the risk of major adverse cardiovascular events in persons with T2DM with pre-existing cardiovascular disease (CVD)." (PMID 32308645, 2020). "However, inhibition of DPP4 may also exacerbate cardiovascular disease by enhancing sympathetic activation and angiogenesis." (PMID 28619058, 2017). "This study assessed the effects of the DPP-4 inhibitor linagliptin versus the sulphonylurea glimepiride and placebo on measures of macro- and microvascular endothelial function in patients with T2D who represented a primary cardiovascular disease prevention population." (PMID 28109295, 2017). "Taken together with our present findings on benefit of linagliptin in premature aging mouse, all these findings support the notion that DPP-4 inhibitors may be a promising anti-diabetic agent for prevention of cardiovascular disease in type 2 diabetic elderly patients." (PMID 29195509, 2017). "The predominant expression of Dpp4 in T cells and upregulation of Dpp4 in aorta‐infiltrating CD4+ T lymphocytes from patients with cardiovascular disease were also noted in the single cell RNA sequencing data obtained from PlaqView." (PMID 36683148, 2023). "In this review, we will focus on the regulatory aspects of DPP4 on chemokines, such as SDF-1, and its potential implications in the pathogenesis and management of cardiovascular disease." (PMID 26441982, 2015). "Among patients with prior cardiovascular disease, the increased 3‐point MACE risk associated with high‐affinity sulfonylureas was attenuated and not statistically significant compared with DPP‐4 inhibitors (HR, 1.07; 95% CI, 0.98–1.17)." (PMID 41017568, 2025). "Despite substantial evidence from extensive cardiovascular outcome trials supporting the cardiovascular safety of dipeptidyl peptidase-4 (DPP-4) inhibitors, no benefit in preventing cardiovascular disease has been observed." (PMID 37920618, 2023). "Previous meta-analyses of DPP-4 inhibitors in cardiovascular diseases have demonstrated decreases in cardiovascular events, while large-scale clinical trials have found that DPP-4 inhibitors neither increased nor decreased the onset of cardiovascular events." (PMID 27351380, 2016). "Recent studies reported that the rates of cardiovascular diseases were not increased with DPP-4 inhibitors." (PMID 25699116, 2015). "There are a number of clinically approved drugs, including DPP4 inhibitors and parathyroid hormone, which have the ability to enhance SDF-1/CXCR4 responsiveness and may improve the outcome of cardiovascular diseases." (PMID 26441982, 2015). "Several recent large scale clinical trials have indicated that unlike most other oral anti-diabetic drugs that promote cardiovascular disease, DPP4 inhibitors are safe from cardiovascular standpoint despite lack of evidence showing beneficial effect." (PMID 26441982, 2015).
cardiovascular disease (continued). "Hence, continuous inhibition of DPP4 activity does not have a major impact on biomarkers of tissue and systemic inflammation in mice or in humans with established cardiovascular disease and T2D." (PMID 32724076, 2020). "Inhibiting DPP4 activity did not change the abundance of circulating DPP4 in serum, although it did reduce the levels of GDF15, a conserved SASP factor and cardiovascular disease biomarker that increased with HFD." (PMID 37097759, 2023). "Although we did not measure serum GLP-1 level in the experiment, decreased DPP-4 level, typically measured in the plasma, is another potential mechanism that GLP-1 may also have beneficial effects in the setting of kidney and cardiovascular disease." (PMID 30823876, 2019).
metabolic disease (59 papers, 2013 to 2026). A congenital disorder (due to inherited enzyme abnormality) or acquired (due to failure of a metabolically important organ) disorder resulting from an abnormal metabolic process. "These variants were selected because previous studies linked rs3788979 to altered DPP4 expression and serum DPP4 levels, and rs12617656 to autoimmune and metabolic disease susceptibility." (PMID 41373842, 2025). "Several DPP4 variants have been associated with altered gene expression, protein levels, and immune pathways, as well as with various autoimmune and metabolic disorders." (PMID 41373842, 2025). "Increased DPP4 activity and levels have been shown to be closely associated with these metabolic diseases." (PMID 34926239, 2021). "Since mRNA expression does not always correlate directly with protein abundance or enzymatic activity, pQTL-based MR could provide complementary insights into the causal role of DPP4 at the protein level in cardiovascular and metabolic diseases." (PMID 40904650, 2025). "Accumulating evidence suggest that among the members if the DPP family, DPP4 is one of the important and abundant serine proteolytic enzyme synthesized by the blood cells and cardiovascular tissues, and that it is relevant to inflammation-associated metabolic disorders and their implications." (PMID 27654253, 2016). "Multiple studies have shown that long-term DPP-4 inhibition effectively ameliorates metabolic disorders and preserves pancreatic functions in diabetic animal models." (PMID 41560728, 2025). "Knockout mouse studies have suggested that DPP4 inhibition has beneficial effects on metabolic diseases." (PMID 39465352, 2024). "Additional administration of DPP4 or SGLT2 inhibitors to patients with T2DM effectively improved metabolic disorders." (PMID 39114607, 2024). "In the DIO mouse model, the DPP-4 inhibitor sitagliptin significantly improved the metabolic disorder exacerbated by niacin, including impaired glucose metabolism, abnormal islet morphology and decreased β cell mass." (PMID 36568082, 2022). "This is likely at the basis of the presence of elevated circulating DPP4 levels in several metabolic diseases." (PMID 36140405, 2022). "This is in line with the known role of DPP4 in metabolic diseases as major incretin hormones responsible for postprandial insulin secretion are among the substrates of its peptidase activity." (PMID 36168895, 2022). "Inhibition of DPP-4 activity to tackle metabolic disorders through the preservation of incretins has been widely described." (PMID 29797022, 2018). "Although these assumptions are controversial, they provide a translational pharmacology approach for the clinical use of DPP-4 inhibitors in the treatment of metabolic diseases." (PMID 28790917, 2017). "Although GLP-1 analog had demonstrated more efficiency on biometric and metabolic disorders than DPP-4 inhibitor, both presented beneficial results on neuro-cardiovascular functions." (PMID 26828649, 2016). "Potentiation of GLP-1 action through receptor agonists has demonstrated efficacy in treating metabolic disease; however, our knowledge of the effects of DPP4 elimination to potentiate endogenous GLP-1 action within the context of chronic liver disease progression is limited." (PMID 36472923, 2023). "However, more intriguing pathways have been described when investigating DPP4 in the context of gut–liver–adipose tissue axis impairment in metabolic disease." (PMID 36140405, 2022). "It is also unknown how much of resistance of endogenous signaling contributes to the heterogeneity observed in metabolic disease and the variable patient responses to pharmacological treatments including DPP4 inhibitors, GLP-1R agonists and bariatric surgery." (PMID 34660576, 2021). "Increased DPP4 circulatory levels, in metabolic diseases, could be explained by an aberrant DPP4 shedding." (PMID 34178021, 2021).
metabolic disease (continued). "Thus, through both its cleavage and regulation of the bioactivity of peptide hormones and its influence on inflammation, DPP4 exhibits a diverse array of effects that can influence the progression of metabolic disease." (PMID 32231442, 2020). "Although its overall significance for the normal physiological regulation of glucose homeostasis in humans and its role in the pathogenesis of the metabolic disease remain to be established, it is evident that DPP4 has the potential to influence glycemic control." (PMID 33312197, 2020). "Up to date, specific mechanistic pathways involved in these pathophysiological processes and organ crosstalk remain incompletely understood, but very recent findings indicate the important role of DPP4 in communication between hepatocytes and adipose tissue in metabolic disease." (PMID 30774748, 2019). "Interestingly, recent findings indicate the important role of dipeptidyl peptidase 4 (DPP4) in the crosstalk between hepatocytes and adipose tissue in metabolic disease." (PMID 30774748, 2019). "Thus, DPP-4 inhibitors evidently have a beneficial effect on metabolic disorders in both pre-diabetic and diabetic women with PCOS, especially if it is administered in combination with metformin." (PMID 29482528, 2018). "Although several types of drugs, such as metformin, thiazolidinediones, dipeptidyl peptidase 4 inhibitors, and α‐glucosidase inhibitors, have been used for the clinical treatment of metabolic disorders, more efficacious drugs with less side effects are needed to treat metabolic disorders." (PMID 39049964, 2024). "In line with these considerations and with findings obtained in animal models, agents specifically modulating DPP4 at the AT level could potentially represent a valid therapeutic option for contrasting the development of metabolic disease in the presence of chronic caloric overload." (PMID 36140405, 2022). "Recent preclinical studies have further expanded the repertoire for the use of DPP4 inhibitors in the treatment of other metabolic diseases and their consequent complications, which may block the signaling pathway of DPP4 with NFκB and matrix metallopeptidase 9 in these patients." (PMID 33614513, 2021). "The novel discovery of the fate of several DPP4+ progenitor cell populations illustrates additional metabolic pathways that may also contribute to the regulation of glucose, insulin sensitivity, and metabolic disease." (PMID 32231442, 2020). "This study aimed to assess the efficacy of combined administration of dipeptidyl peptide-4 (DPP4) and sodium-glucose cotransporter-2 (SGLT2) inhibitors on metabolic disorders and their preferable and complementary effects." (PMID 39114607, 2024). "Although GLP-1 shows therapeutic effects in metabolic diseases, the half-life of GLP-1 is very short and it is quickly cleaved into the inactive truncated form by dipeptidyl peptidase-4 (DPP-4) within a few minutes." (PMID 33732656, 2021). "However, while it is evident that DPP-4 has the potential to influence glycaemic control, its overall significance for the normal physiological regulation of glucose homeostasis in humans and its role in the pathogenesis of metabolic disease remain to be established." (PMID 30828317, 2019). "Notably, certain pharmacological treatments, such as insulin, metformin, and DPP-4 inhibitors, may modify the biological response of diabetic patients during orthodontic treatment, in some cases attenuating the bone remodeling and inflammation that are characteristic of this metabolic disease." (PMID 40725571, 2025). "The investigated parameters related to metabolic disorders included sirtuin 1 (SIRT-1), sirtuin 3 (SIRT-3), sirtuin 6 (SIRT-6), irisin (IRS), myostatin (MSTN), peptide YY (PYY), glucagon-like peptide 1 (GLP-1), and dipeptidyl peptidase 4 (DPP-4)." (PMID 39124846, 2024).
metabolic disease (continued). "Additionally, antidiabetic medications such as metformin, thiazolidinediones (TZDs), dipeptidyl peptidase 4 (DPP-4) inhibitors, and sodium glucose cotransporter 2 (SGLT2) inhibitors are currently used to improve insulin sensitivity and glycemic control in individuals with metabolic diseases." (PMID 37240157, 2023). "Aim of this study was to investigate hepatic and systemic DPP4 levels/activity in relation to NAFLD/NASH in individuals with and without metabolic disease." (PMID 32852705, 2021).